HTT-AS (HTT antisense RNA)
Synonyms: HTTAS; HTT-AS1
Gene: Long non-coding RNA gene on chromosome 4 (3,046,139 to 3,074,624, reverse strand). Ensembl gene ENSG00000251075.
Gene Ontology:
Biological process: regulation of gene expression
Diseases named in the same sentence as HTT-AS in open-access papers:
HTT-AS is named in the same sentence as 1 disease in open-access papers, as found by Europe PMC text mining. Sharing a sentence is not in itself a finding about the gene and the disease. The quoted sentences say what the papers report.
gastric cancer (1 paper, 2022). A primary or metastatic malignant neoplasm involving the stomach. "Even though, there is no direct evidence showing that HOTAIR and HTTAS relate to gastric cancer so far, some studies found that HOTAIR has stable expression in peripheral blood and can be used as a non-invasive diagnostic marker for gastric cancer." (PMID 36338997, 2022).